PAGE5 (PAGE family member 5)
Synonyms: PAGE-5; CT16.1; GAGEE1; CT16.2; CT16
Tractability: PROTAC: ubiquitination databases record sites on it.
Gene: Protein-coding gene on chromosome X (55,220,346 to 55,224,108, forward strand). Ensembl gene ENSG00000158639.
Subcellular location (Human Protein Atlas): Mitochondria
Gene Ontology:
Molecular function: protein binding
Homologues: Orthologues: chimpanzee PAGE5 (97% identical), macaque PAGE2B (90% identical), pig PAGE2B (53% identical). Paralogues in human: PAGE2B (89% identical), PAGE2 (83% identical), PAGE3 (44% identical), PAGE4 (41% identical), XAGE5 (35% identical), GAGE10 (34% identical), PAGE1 (33% identical), XAGE2 (32% identical), XAGE3 (32% identical), GAGE1 (31% identical), GAGE13 (31% identical), GAGE2A (31% identical), and 10 more.
Diseases named in the same sentence as PAGE5 in open-access papers:
PAGE5 is named in the same sentence as 12 diseases in open-access papers, as found by Europe PMC text mining. Sharing a sentence is not in itself a finding about the gene and the disease. The quoted sentences say what the papers report.
melanoma (3 papers, 2012 to 2022). A malignant, usually aggressive tumor composed of atypical, neoplastic melanocytes. "Knockdown of PAGE5 in melanoma cells resulted in a decrease in cell survival when cells were exposed to apoptosis‐inducing cisplatin." (PMID 30283907, 2018). "CT antigen 16 (CT16, PAGE5) is frequently expressed in advanced melanoma but its biological function has been unknown." (PMID 23028975, 2012).
psychosis (2 papers, 2017 to 2021). "In conclusion, we found that a subgroup of patients with first-episode psychosis was seropositive to the N-terminal portion of the PAGE protein family (PAGE2B/PAGE2/PAGE5), and that such seropositivity was associated with the development of schizophrenia." (PMID 28742074, 2017). "Among the three types of autoantibodies with a significantly different distribution pattern in patients versus controls, autoantibodies toward the N-terminal portion of the PAGE protein family (PAGE2B/PAGE2/PAGE5) were exclusively seen in patients with first-episode psychosis." (PMID 28742074, 2017). "Additional studies are necessary to confirm these findings and to elucidate whether PAGE2B, PAGE2, PAGE5 or another protein cross-reactive to the N-terminal end of PAGE2B is the critical autoantibody target, and to further disentangle its role in the etiopathology of psychosis." (PMID 28742074, 2017).
breast carcinoma (1 paper, 2023). "Our study constructed the prognostic signature based on breast cancer PD-1/PD-L1 pathway molecular typing-related genes (IFNG, JCHAIN, ELOVL2, PIGR, PAGE5, ACTL8, and CLEC3A)." (PMID 37154982, 2023).
germ cell tumor (1 paper, 2025). A benign or malignant, gonadal or extragonadal neoplasm that originates from germ cells. "Together, these findings suggest that DPPA4 and PSMA7 promote tumor progression, whereas PAGE5 and SAT1 suppress progression in germ cell tumors." (PMID 41203637, 2025).
osteosarcoma (1 paper, 2024). A usually aggressive malignant bone-forming mesenchymal neoplasm, predominantly affecting adolescents and young adults. "Although the roles of SP110, HHAT, MORC4, PAGE5, MAP7, and CAMK1G in osteosarcoma have rarely been reported, their involvement in other types of cancer has been revealed." (PMID 39980969, 2024).
seminoma (1 paper, 2025). A radiosensitive malignant germ cell tumor found in the testis (especially undescended), and extragonadal sites (anterior mediastinum and pineal gland). "In contrast, PAGE5 and SAT1, predominantly expressed in non-metastatic seminoma, were associated with reduced metastatic potential and a lower likelihood of disease progression." (PMID 41203637, 2025).
small cell lung carcinoma (1 paper, 2024). Small cell lung cancer (SCLC) is a highly aggressive malignant neoplasm, accounting for 10-15% of lung cancer cases, characterized byrapid growth, and early metastasis. "PAGE5 was reported to act as a mediator of chemoresistance in human small cell lung cancer." (PMID 39980969, 2024).
tumor (1 paper, 2025). "Conversely, tumor cells overexpressing PAGE5 and SAT1 exhibited reduced stemness, migratory capacity and proliferation." (PMID 41203637, 2025).
PAGE5 also shares sentences with these, for which no sentence is quoted: cancer (4 papers); infection (1); prostate carcinoma (1); schizophrenia (1).